SLC1A2 (solute carrier family 1 member 2)
Diseases named in the same sentence as SLC1A2 in open-access papers (continued):
Sharing a sentence is not in itself a finding about the gene and the disease.
cancer (11 papers, 2013 to 2025). A tumor composed of atypical neoplastic, often pleomorphic cells that invade other tissues. "For instance, miR-145 is known to regulate several transporters of the ABC1 family and SLC1A2, which are important regulators of drug entry in cancer cells." (PMID 33081077, 2020). "However, as glutamate is a major excitatory neurotransmitter of the central nervous system, a monoclonal antibody targeting SLC1A2 might provide an alternative anti-cancer agent, where the larger size would limit crossing the blood-brain barrier." (PMID 23637631, 2013). "We discovered novel gene rearrangements in diverse human cancer types, including fusions of ROS1, SLC1A2, RAF1, EWSR1, CDK6, and CLTC." (PMID 23637631, 2013). "miR-199b-5p targets solute carrier transporters (SLC1A2/EAAT2 in astrocytes and SLC38A2/SNAT2 and SLC16A7/MCT2 in neurons) to hijack the neuron–astrocyte metabolic coupling, leading to extracellular retention of these metabolites and promoting cancer cell growth." (PMID 38811525, 2024). "We identified new gene fusions involving ROS1, SLC1A2, RAF1, EWSR1, CDK6, and CLTC, some occurring in cancer types not previously known to harbor fusions." (PMID 23637631, 2013).
genetic diseases (1 paper, 2022). "The linkage of human genetic diseases to genes encoding EAAT1 (SLC1A3), EAAT2 (SLC1A2) and EAAT3 (SLC1A1) revealed additional roles of EAATs in cell and organ physiology." (PMID 33587237, 2022).
SLC1A2 also shares sentences with these, for which no sentence is quoted: Cerebral ischemia (36 papers); ischemia (35); Stroke (25); Huntington disease (20); temporal lobe epilepsy (12); brain injury (11); dementia (11); glioblastoma (11); psychiatric disorder (10); infarction (6); Ataxia (5); injury (5); migraine (5); multiple sclerosis (5); Parkinson’s (5); alcohol use disorder (4); brain diseases (4); brain tumors (4); cerebral palsy (4); Hyperammonemia (4); memory impairment (4); mood disorder (4); alcoholism (3); amyloid (3); brain cancer (3); brain infarction (3); cocaine addiction (3); diabetes (3); frontotemporal dementia (3); HIV-associated neurocognitive disorder (3).
A further 115 diseases each share a sentence with SLC1A2 in 3 papers or fewer.